C3 (complement C3)
Diseases named in the same sentence as C3 in open-access papers (continued):
Sharing a sentence is not in itself a finding about the gene and the disease.
chronic obstructive pulmonary disease (6 papers, 2011 to 2024). A chronic and progressive lung disorder characterized by the loss of elasticity of the bronchial tree and the air sacs, destruction of the air sacs wall, thickening of the bronchial wall, and mucous accumulation in the bronchial tree. "In a mouse model of chronic obstructive pulmonary disease, C3 presented anti-oxidative effects as an important pro-survival molecule in airway epithelial cells." (PMID 39272977, 2024). "A previous study showed that intracellular C3 was upregulated in airway epithelial cells (AECs) from individuals with end-stage chronic obstructive pulmonary disease (COPD)." (PMID 36605203, 2022).
clear cell renal cell carcinoma (6 papers, 2020 to 2025). "In a clear-cell renal cell carcinoma murine model, C3 has been proven to be associated with tumor-associated macrophages (TAMs) infiltration and tumor growth." (PMID 35169832, 2022). "In a clear-cell renal cell carcinoma (ccRCC) model, mice deficient in C1q, C4, or C3 displayed decreased tumor growth, whereas tumors infiltrated with high densities of C1q-producing macrophages exhibited an immunosuppressed microenvironment." (PMID 33033253, 2020).
coagulopathy (6 papers, 2012 to 2025). "First, we found that the elevated levels of NETs and complement C3 were closely related to immune status, coagulation disorders, and multiple organ dysfunction." (PMID 33557911, 2021). "Remarkably, main hub proteins in the CR group were VTN, C3, C4B, C9, and CFH that play a major role in the complementary pathway, which has gained increased attention as a major contributor to cancer‐related coagulopathy." (PMID 40079446, 2025).
Constipation (6 papers, 2015 to 2025). Infrequent or difficult evacuation of feces. "Background/Objectives: Constipation can be induced in animal models through various factors such as loperamide (Lop) or complement component 3 (C3) deficiency." (PMID 41011160, 2025). "In this study, we sought to identify a novel gene associated with C3 deficiency-induced constipation using microarray analyses." (PMID 39273477, 2024). "Meanwhile, we selected seven genes that were expected to play an important role in C3 deficiency-induced constipation from a total of 2529 genes differentially expressed between WT and C3 KO mice." (PMID 39273477, 2024). "In the present study, the expression levels of the EDN1 and NXPE4 genes were upregulated 2.06- and 2.00-fold, respectively, during C3 deficiency-induced constipation." (PMID 39273477, 2024). "The regulatory factors for 5-HT and ACh function were analyzed in the mid colon of C3 KO mice with constipation to determine if C3 deficiency-induced constipation was accompanied by an alteration on the excitatory function of ENS in the mid colon." (PMID 35743302, 2022). "This study measured the expression levels of NSE, PGP9.5, and C-kit markers in the mid colon of C3 KO mice to indirectly determine if C3 deficiency-induced constipation is accompanied by changes in the density of enteric neurons and ICC." (PMID 35743302, 2022). "The present study investigated the levels of C3a and C3bR expression in the mid colon of C3 KO mice during C3 deficiency-induced constipation." (PMID 35743302, 2022). "The present study investigated alterations in the excitatory function of ENS in the mid colon of C3 KO mice during C3 deficiency-induced constipation." (PMID 35743302, 2022). "In the present study, we investigated the effects of dysbiosis on the fecal microbiota of C3 KO mice during C3 deficiency-induced constipation." (PMID 34349661, 2021). "Taken together, our data indicate that C3 deficiency-induced constipation is associated with increases in seven genera of bacteria and decreases in five bacteria genera present in fecal microbiota." (PMID 34349661, 2021). "Further research using mucosal tissue of C3 KO mice is required to elucidate the overall composition of the colonic mucosal microbiota and verify the critical role of dysbiosis in C3 deficiency-induced constipation." (PMID 34349661, 2021). "Moreover, the lack of analyses of the molecular mechanism of the effects of C3 deficiency-induced constipation in the transcriptional regulation of colon-expressed genes should be considered a drawback of this study." (PMID 39273477, 2024). "These mice also showed dysregulation of the composition of neuronal and interstitial cells of Cajal (ICC), the excitatory and inhibitory transmission of the enteric nervous system (ENS), and expression of C3 receptors in the mid colon during C3 deficiency-induced constipation." (PMID 39273477, 2024). "Thus, the expression of the ALPI gene and its effects on mucin secretion ability and water retention capacity in C3 deficiency-induced constipation was first investigated in the epithelial cells derived from the C3 KO mice." (PMID 39273477, 2024). "However, no studies to date have attempted to identify the novel genes that play an important role in C3 deficiency-induced constipation despite scientific evidence that C3 deficiency is an important cause of constipation." (PMID 39273477, 2024). "Given that the feeding parameters for all three groups were maintained at constant levels, these results suggest that C3-deficiency-induced constipation could be alleviated by the administration of Urd and AEtLP, as observed for Lop-induced constipation." (PMID 37958740, 2023). "This study examined whether C3 deficiency-induced constipation may be accompanied by NO-mediated inhibitory function of ENS in the mid colon." (PMID 35743302, 2022).
Constipation (continued). "This section investigates whether C3 deficiency-induced constipation was accompanied by an alteration in the inhibitory function of ENS in the mid colon." (PMID 35743302, 2022). "The present study first suggests that C3 deficiency-induced constipation is associated with a decrease in the density of enteric neurons and ICC, a decline in 5-HT and ACh concentration, and an increase in the NO concentration for ENS function in the mid colon." (PMID 35743302, 2022). "This study examined whether C3 deficiency-induced constipation can be accompanied by a dysfunction of the ENS in the mid colon of C3 KO mice." (PMID 35743302, 2022). "This study investigated whether C3 deficiency-induced constipation is accompanied by alterations in the excitatory and inhibitory function of ENS in the mid colon of C3 KO mice." (PMID 35743302, 2022). "On the other hand, whether C3 deficiency-induced constipation can be accompanied by a dysfunction of the ENS in the mid colon of C3 KO mice remains to be determined." (PMID 35743302, 2022). "The present results suggest that C3 deficiency-induced constipation may be associated with 1237 upregulated genes including PNLIP, CEL, CPB1, CTRL, PNLIPRP1, and REG1 as well as 1292 downregulated genes including Eif2s3y, UTY, KDM5D, IGKV6-32, Olfr870, and DDX3Y." (PMID 39273477, 2024). "In the present study, the laxative effects of Urd and AEtLP were examined in C3 KO mice with C3-deficiency-induced constipation to investigate whether substances that have therapeutic effects on Lop-induced constipation are also effective in C3-deficiency-induced constipation." (PMID 37958740, 2023). "The alterations in the intestinal length and the charcoal meal transit were analyzed in C3 KO mice treated with Urd and AEtLP to investigate whether the laxative effects of Urd and AEtLP in C3-deficiency-induced constipation were accompanied by an improvement in the GI motility and length." (PMID 37958740, 2023). "These levels were differentially improved in the C3 KO (45 and 58%) and Lop-induced constipation models (48 and 32%) after the administration of Urd and AELP." (PMID 41011160, 2025). "In this study, we compared the therapeutic effectiveness of Urd and AELP on GI transit in C3 KO and Lop-induced constipation models." (PMID 41011160, 2025). "Treatment with Urd and AELP significantly inhibited receptor protein kinase kit (c-Kit), protein gene product 9.5 (PGP9.5), and neuron-specific enolase (NSE) expressions in the C3 KO model than in the Lop-induced constipation model." (PMID 41011160, 2025). "Subsequently, the function of the key gene candidates was further verified by a recovery study in the intestinal epithelial cells of C3 KO mice with constipation phenotypes." (PMID 39273477, 2024). "Of the ten up-regulated genes, the largest decrease in the transcripts of constipation rats was observed for Serpina3n (0.19-fold), followed Lcn2, Slc5a8, C3, Rerg, and Arhgap8." (PMID 26151867, 2015). "Moreover, the transcription of CACNA1C in the Urd-treated C3 KO model was higher than in the Lop-induced constipation model, while, after treatment with AELP, the transcription of CACNA1C was greater in the Lop-induced constipation model than in the C3 KO model." (PMID 41011160, 2025). "In addition, Urd and AELP were specifically selected as a single chemical drug and a natural product with laxative effects, respectively, because their therapeutic effects were successfully demonstrated in the Sprague-Dawley (SD) rat model with Lop-induced constipation and the C3 KO mice model." (PMID 41011160, 2025). "Therefore, C3 deficiency-induced constipation may be associated with a dysregulation of the excitatory function of ENS through upregulation of the NO concentration and iNOS expression in the mid colon of C3 KO mice." (PMID 35743302, 2022).
Constipation (continued). "In this study, we characterized alterations in the fecal microbiota of C3 KO mice with constipation phenotypes, and the role of their fecal dysbiosis on defecation delay was verified in an FMT study that transferred fecal of C3 KO mice into WT mice." (PMID 34349661, 2021). "Our results provide the first evidence that C3 deficiency can be considered to be a cause for the upregulation of CLCN2, unlike their levels in Lop-induced constipation." (PMID 41011160, 2025).
cutaneous squamous cell carcinoma (6 papers, 2019 to 2025). "In the DMBA-TPA model of cutaneous squamous cell carcinoma (cSCC), which depends on chronic inflammation, loss of C3 provided protection against tumor development." (PMID 41300283, 2025). "C3 was recently showed to play a role in cutaneous squamous cell carcinoma, as C3 deficient mice developed fewer and smaller tumors compared to wild type controls." (PMID 35860237, 2022). "Additionally, C3 was consistently overexpressed across cancers, supporting its tumor-promoting role, as evidenced by reduced tumor growth in C3-deficient mice in lung, breast, and cutaneous squamous cell carcinoma models." (PMID 40283026, 2025). "C3 is upregulated in skin squamous cell carcinoma and promotes the growth of cutaneous squamous cell carcinoma." (PMID 34722636, 2021). "Complement C3 has been shown to be highly expressed in cutaneous squamous cell carcinoma (cSCC) tumour tissues and is correlated with tumour cell growth." (PMID 30825266, 2019).
cutaneous vasculitis (6 papers, 2018 to 2024). Inflammation of the blood vessel wall characterized by palpable purpura. "Mast cells contribute to the pathogenesis of cutaneous vasculitis through complement C3 that is cleaved to C3b and then to iC3b by complement factor I. The receptor of iC3b, CD11b, is expressed on neutrophils and monocytes and CD14 on monocytes." (PMID 35747245, 2022).
cyst (6 papers, 1994 to 2024). A sac-like closed membranous structure that may be empty or contain fluid or amorphous material. "We tested the causal relationship between complement activation and cyst growth using a Pkd1KO renal tubular cell line and newly generated conditional Pkd1–/–C3–/– mice." (PMID 38912583, 2024). "Reactive astrocyte A1 type expended as complement component 3 (C3) was expressed in the cyst area." (PMID 38650015, 2024). "Our mouse model allowed us to primarily demonstrate that C3 deficient mice were refractory to the development of endometriotic lesions, whereas WT mice developed a higher number of EM cysts, suggesting that the lack of C3 prevented the EM cyst formation." (PMID 34489939, 2021).
emphysema (6 papers, 2011 to 2025). "Our findings confirm the relationship between C3 and COPD and emphysema and further suggest that it is partly mediated through C3 genetic variants." (PMID 27532455, 2016). "More recently, complement component C3d was proposed, since it correlates with both radiographic emphysema and severity of the emphysema in AATD, but not in usual COPD; also, in PiZZ AATD after intravenous AT, AAT disrupts C3 activation, thereby decreasing C3d plasma levels." (PMID 33659933, 2020).
epidermolysis bullosa acquisita (6 papers, 2012 to 2024). "In contrast, C3 deposition was effectively detected in a mouse model of epidermolysis bullosa acquisita, where complement activation is a crucial step in disease progression." (PMID 39737181, 2024). "Surprisingly, the pathologist also found IgG and C3 deposition that were compatible with the epidermolysis bullosa acquisita (EBA)." (PMID 34680898, 2021). "Epidermolysis bullosa acquisita exhibits extensive IgG/C3 staining with less IgA and IgM seen at the basement membrane." (PMID 23110919, 2012).
experimental autoimmune encephalomyelitis (6 papers, 2011 to 2025). An autoimmune demyelinating disease of the central nervous system that is produced experimentally in animals by the injection of homogenized brain or spinal cord in Freund's adjuvant. "(G, I) Representative images of RNAscope labeling for (G) Fcgr3, B2m, Cd74, and (I) Gfap, C3 in Swiss Jim Lambert (SJL) mice 11 weeks after experimental autoimmune encephalomyelitis (EAE) induction." (PMID 39475792, 2024). "For example, a study with C3 KO mice indicates the requirement of C3 for development of maximal experimental autoimmune encephalomyelitis (EAE) disease." (PMID 36741417, 2022). "Likewise, a study using the experimental autoimmune encephalomyelitis (EAE) model found elevated C3 was secreted by neurodegenerative astrocytes." (PMID 40076480, 2025).
hepatitis B (6 papers, 2009 to 2024). "Serologic studies for hepatitis B and C were negative in 98% of patients (52/53); 1 patient had a positive test for hepatitis B. C3 and/or C4 were decreased in 56% (43/77)." (PMID 39156178, 2024). "Vasculitis and infectious panels were unremarkable except for low complement C3 and evidence for previous hepatitis B infection." (PMID 38344578, 2024). "The increase or decrease of C3 appears to be based on the type and stage of hepatitis B infection." (PMID 26760961, 2016). "Serologic studies were negative for ANA, anti-GBM, ANCA, hepatitis B, and hepatitis C. Serum C3 and C4 level were normal." (PMID 29348949, 2017). "ANA was detectable in two patients in low titer (≤1: 160), and anti-Ro, anti-La, anti-Smith, ant-RNP, RF, p- and c-ANCA, protein electrophoresis, C3 and C4 complement and markers of hepatitis B and C were negative." (PMID 20204175, 2009).
Hypercholesterolemia (6 papers, 2012 to 2024). An increased concentration of cholesterol in the blood. "Plasma levels of LTB4, whichpromotes atherosclerosis, are elevated in hypercholesterolemic rats.Activated C3 is elevated in hypercholesterolemic apo-E-null mice and patientswith familial hypercholesterolemia." (PMID 39077184, 2022). "Moreover, correlation analysis indicated that C3 correlated positively with serum cholesterol and DD and negatively with total protein and albumin, suggesting that renal tubular C3 deposition may aggravate hypercholesterolemia, hypercoagulability, and hypoproteinemia." (PMID 30003098, 2018).
hypercoagulation (6 papers, 2014 to 2025). "According to the results, the PPP samples with the added C3 and TNF-α showed that more parameters point towards hypercoagulation, thus suggesting these molecules have a more profound effect on fibrin formation." (PMID 29379088, 2018).
hypothyroidism (6 papers, 2010 to 2023). Abnormally low levels of thyroid hormone. "Similarly, C3/C4 complement system is reported to be overactivated in hypothyroidism patients." (PMID 36672757, 2022).
immune deficiency (6 papers, 2008 to 2025). "Based on time to death following footpad inoculation, C3 deficiency resembled immunodeficiencies of other important components of the antiviral response, specifically CD8+ T cells, NK cells, and IFN-γ." (PMID 19112490, 2008). "In children with CGD, where the number of B cells recovered is low, more complement is beneficial to balance the immune deficiency caused by insufficient number of B cells, so the higher level of C3 and C4 in children with CGD may be a feedback effect from insufficient number of B cells." (PMID 37388746, 2023). "In our opinion, any DGI should be screened for classical immune deficiency with HIV serology, protein electrophoresis, and complement assay with C3 C4 and CH50." (PMID 40302718, 2025). "We hypothesize that the isolated C3 deficiency in this case represents a temporary state of complement consumption associated with hemorrhage and tissue injury, rather than an underlying immunodeficiency or primary glomerular disorder." (PMID 40995257, 2025). "Immune function test indicated immunodeficiency (CD4+ T lymphocyte 192/mL, CD8+ T lymphocyte 168/mL, CD3+ T lymphocyte 380/mL, serum C3 0.81 g/L, serum C4 0.08 g/L)." (PMID 36246283, 2022).
leptospirosis (6 papers, 2012 to 2025). A contagious bacterial infection caused by spirochetes of the genus Leptospira. "However, 1-month post-infection appears to be a critical time point in murine leptospirosis if C3 deficiency is present, as both leptospiral load in the kidney and fibrosis formation were more pronounced at this stage." (PMID 41251377, 2025). "Notably, C3 also influences the differentiation of helper and cytotoxic T lymphocytes into effector cells, potentially contributing to the increased severity of chronic leptospirosis observed in C3-deficient animals." (PMID 40236016, 2025). "Our objective is to understand the immune response in leptospirosis, specifically the role of the Complement C3 protein." (PMID 40236016, 2025). "In the present study, we investigated the role of C3 in a chronic model of leptospirosis using L. interrogans serovar L1-130 FIOCRUZ (LIC)." (PMID 41251377, 2025). "Our findings highlight the potential role of C3 in regulating effector helper and cytotoxic T lymphocytes, serving as a key link between the innate and adaptive immune system in leptospirosis." (PMID 41251377, 2025). "The deposition of IgM, IgA, IgG and C3 in the alveolus of patients with pulmonary hemorrhage secondary to leptospirosis and in a guinea pig model of severe pulmonary leptospirosis is similar to the pattern seen in Goodpasture’s syndrome." (PMID 23809518, 2013). "Interestingly, interstitial nephritis was observed in C3KO mice at 15 d.p.i., raising new questions about the role of C3 beyond the acute phase of leptospirosis, particularly after kidney colonization has been established." (PMID 41251377, 2025). "However, the mechanisms driving the progression from the acute to the chronic stage of leptospirosis, and if C3 plays a role in this process, remain unknown." (PMID 41251377, 2025). "Additionally, murine C3 deficiency impairs the differentiation of naïve T cells into effector helper and cytotoxic T lymphocytes in the kidney and lymph nodes after 30 d.p.i., suggesting that the depletion of cytotoxic T lymphocytes in the absence of C3 may contribute to chronic leptospirosis." (PMID 41251377, 2025). "Overall, the absence of C3 does not impact mouse survival during leptospirosis." (PMID 41251377, 2025).